GRK5 (G protein-coupled receptor kinase 5)
Diseases named in the same sentence as GRK5 in open-access papers (continued):
Sharing a sentence is not in itself a finding about the gene and the disease.
cardiac hypertrophy (continued). "Although GRK2 has thus far been the primary focus of drug discovery efforts, GRK5 has been increasingly targeted as a potential treatment for cardiac hypertrophy." (PMID 25340299, 2014). "Regardless, the GRK1·amlexanox structure will serve as a useful platform to begin rational design of amlexanox-based therapeutics for the treatment of either cardiac hypertrophy (GRK5) or, by extension, diabetes (IKKε)." (PMID 25340299, 2014). "It remains to be determined to what extent the ability of GRK5 to bind IκBα in the context of the intact kinase is responsible for the exaggerated cardiac hypertrophy observed following TAC in transgenic mice with cardiac overexpression of GRK5." (PMID 23658733, 2013). "Once in the nucleus, GRK5 imparts a crucial GPCR-independent activity to facilitate cardiac hypertrophy." (PMID 23472081, 2013). "For example, transgenic mice with cardiac-specific overexpression of GRK5 demonstrate intolerance to ventricular pressure-overload, as evidenced by augmented cardiac hypertrophy and accelerated HF following aortic banding." (PMID 23472081, 2013). "Surprisingly, we found that after only 3 days of treatment with AngII, Tg-GRK5 mice had slight, but significant cardiac hypertrophy." (PMID 23472081, 2013). "To further advance our understanding of hypertrophic agonist-induced nuclear GRK5 localization, we investigated select Gq-coupled receptor ligands known to induce cardiac hypertrophy." (PMID 23472081, 2013). "GRK5 expression in vivo promotes TAC-induced activation of a program of gene transcription required for cardiac hypertrophy." (PMID 23658733, 2013). "While the canonical role of GRKs is to phosphorylate and induce receptor desensitization/recycling, it has been shown that GRK5 can also translocate to the nucleus of cardiomyocytes where it can exert GPCR-independent effects promoting maladaptive cardiac hypertrophy and dysfunction." (PMID 33560342, 2022). "GRK5 fibroKO hearts were protected against cardiac hypertrophy post-MI." (PMID 33500351, 2021). "Mechanistic analysis demonstrated that GRK5-induced cardiac hypertrophy was associated with its non-canonical activity in the nucleus of cardiomyocytes." (PMID 33466800, 2021). "Furthermore, in addition to phosphorylating HDAC5 in the nucleus, GRK5 contributes to pathological cardiac hypertrophy by activating nuclear factor of activated T cells (NFAT) transcription factor in phosphorylation-independent manner via direct binding." (PMID 30837883, 2019). "Indeed, GRK5 exacerbates cardiac hypertrophy by phosphorylation of different substrates (plasma membrane receptors and transcription factors)." (PMID 29543709, 2018). "Other calcium-calmodulin dependent pathways are involved in the development of cardiac hypertrophy, such as CaMKs signaling, and we cannot exclude the possibility that they could be affected by GRK5-NT." (PMID 29543709, 2018). "However, cardiac hypertrophy and failing heart after pressure overload are detected in transgenic mice with cardiac-specific overexpression of GRK5." (PMID 30538631, 2018). "At the specific disease level, the expressional regulation and activity of GRK5 has been linked with multiple age-related diseases such as type 2 diabetes mellitus (T2DM), cardiac hypertrophy, hypertension, Parkinson’s disease, and Alzheimer’s pathology in mice and humans." (PMID 30618771, 2018). "Demonstrating its close functional association with GRK5 signaling paradigms, HDAC6 expression and activity has been shown to be significantly elevated in stressed cardiac muscle, while remaining unchanged in physiological cardiac hypertrophy models." (PMID 30618771, 2018). "Far fewer selective inhibitors have been reported for GRK5, a target for the treatment of cardiac hypertrophy, and the mechanism of action of reported compounds is unknown." (PMID 25340299, 2014). "Recently, we addressed the role of endogenous GRK5 in the setting of cardiac hypertrophy." (PMID 23472081, 2013).
cardiac hypertrophy (continued). "Notably, this dose and treatment schedule of AngII in NLC mice did not lead to increased cardiac size, indicating that AngII-driven nuclear GRK5 seen in Tg-GRK5 mice can induce and potentiate cardiac hypertrophy." (PMID 23472081, 2013). "GRK5 can function in the nucleus to regulate cardiac hypertrophy." (PMID 23658733, 2013). "However, TBX5, TBX20, ERBB4, and GRK5, which have been linked to the proliferation of fetal and neonatal cardiomyocytes [TBX5, TBX20, ERBB4] and cardiac hypertrophy [GRK5], were upregulated in the CM1 cluster, as well as in Fetal cardiomyocytes." (PMID 35860330, 2022). "Moreover, transcriptome unbiased analysis of post-MI cardiomyocytes with GRK5 overexpression showed altered levels of several genes previously indicated to be involved in cardiac hypertrophy, remodeling or HF such as Kcne1, Efna5, Psmd8 and several regulators of the extracellular matrix." (PMID 33560342, 2022). "GRK5 activity in the nucleus may be associated with a progression of a maladaptive cardiac hypertrophy that is independent of βARs." (PMID 30538631, 2018). "However, aldosterone-induced cardiac hypertrophy is totally prevented in Grk5 KO mice." (PMID 26932512, 2016). "GRK5-mediated HDAC5 phosphorylation and the ability of GRK5 to regulate IκBα function represent two mechanisms whereby cardiac overexpression of GRK5 could cause pathological cardiac hypertrophy in response to pressure overload in mice." (PMID 23658733, 2013). "G protein-coupled receptor kinase 5 (GRK5) is upregulated in failing human myocardium and promotes maladaptive cardiac hypertrophy in animal models." (PMID 33560342, 2022). "One example of such regulation is GRK5-dependent phosphorylation of class II histone deacetylase 5 (HDAC5), which plays a role in pathological cardiac hypertrophy." (PMID 30837883, 2019). "Cardiomyocyte-specific deletion of GRK5 did not influence cardiac hypertrophy in post-sham or -MI mice from both sexes compared to surgery-matched WT groups." (PMID 33560342, 2022). "Importantly, this finding was confirmed by EMSA assay, which shows that GRK5-NT significantly reduces both NFAT and GATA-4 ability to bind DNA in an established model of cardiac hypertrophy (i.e., SHR)." (PMID 29543709, 2018). "Moreover, through a GRK5 knockdown assay, we confirmed the absolute requirement of GRK5 in MEF2 activation and in cardiac hypertrophy downstream of aldosterone." (PMID 26932512, 2016). "Interestingly, and in contrast to the reported overexpression of GRK2 in VSMCs, the elevation of GRK5 expression failed to induce any significant cardiac hypertrophy." (PMID 30618771, 2018). "However, when GRK5-ΔNLS was overexpressed, there was no nuclear GRK5 localization and significantly diminished aldosterone-dependent cardiac hypertrophy." (PMID 26932512, 2016). "However, consistent with the role of GRK5 (in the nucleus) in pathological cardiac hypertrophy, no PW increase was observed in Grk5 KO mice." (PMID 26932512, 2016). "A mutation within the amino-terminus of GRK5 negating CaM binding attenuates GRK5 movement from the sarcolemma to the nucleus and, importantly, overexpression of this mutant does not facilitate cardiac hypertrophy and related gene transcription in vitro and in vivo." (PMID 23472081, 2013). "However, the extent to which either of these mechanisms are actually responsible for GRK5-dependent cardiac hypertrophy in vivo and whether they represent the only means by which GRK5 promotes hypertrophy is not known." (PMID 23658733, 2013). "In fact, AngII, which is a potent inducer of myocardial hypertrophy, can induce GRK5 translocation to the nucleus and interestingly, the AT1R is not a target of GRK5-mediated desensitization." (PMID 26932512, 2016).
Obesity (10 papers, 2014 to 2025). Accumulation of substantial excess body fat. "These important mechanistic in vitro studies support previous in vivo studies implicating Grk5 as a causal gene for obesity." (PMID 39838122, 2025). "G protein-coupled receptor kinase 5 (GRK5) is implicated in the pathogenesis of obesity in both humans and rodent models." (PMID 40666930, 2025). "GRK5 has a key role in several diseases; for example, GRK5 is a decisive pathogenic factor in early Alzheimer’s disease, hepatic steatosis and metabolic disorders such as type II diabetes and obesity, injured and failing heart and cancer." (PMID 33841542, 2020). "Previous studies have identified G protein-coupled receptor (GPCR) kinase 5 (GRK5) as a genetic factor contributing to obesity pathogenesis, but the underlying mechanism remains unclear." (PMID 38798474, 2024). "These in vitro studies provide important mechanistic support for the role of GRK5 in adipogenesis and are in-line with previous in vivo studies which implicate GRK5 as an important obesity gene." (PMID 39838122, 2025). "Previous studies have reported that deletion of Grk5 results in decreased adipocyte differentiation and protection against diet-induced adiposity, supporting GRK5 signaling as a therapeutic target for obesity." (PMID 40666930, 2025). "Our findings also differ from the whole body Grk5 KO mouse model, which protected against diet-induced obesity." (PMID 40666930, 2025). "Here, we assessed the small-molecule GRK5 inhibitor, GRK5-IN-2, for its effects on metabolic tissues and therapeutic potential in a diet-induced obesity mouse model." (PMID 40666930, 2025). "The results revealed that 18 of the DMR genes were associated with addiction and obesity (ADCY3; ADCY9; ATF4; CDK5R1; CHRNB2; GABRD; GABRG3; GNB1; GNB3; GRK5; HDAC4; HDAC9; MAP2K1; PDE11A; PDE2A; PDE3A; PPP1CA; SLC6A3)." (PMID 34389046, 2021). "High expression of GRK5 has been reported in several pathologies including cardiac hypertrophy and heart failure, hypertension, cancer, obesity and diabetes." (PMID 29773828, 2018). "Genetically modified mice models suggest an important role for G-protein-coupled receptor kinase 5 (GRK5) in the pathophysiology of obesity and related disorders." (PMID 29773828, 2018). "For instance, the GRK5 regulates the GPCR signaling pathway and GRK5 deficiency led to insulin resistance and hepatic steatosis, or decreases diet-induced obesity and adipogenesis in mice." (PMID 25250046, 2014). "We further found that Grk5 mRNA is more abundant in stromal vascular (SV) fractions than in adipocyte fractions isolated from the epidydimal visceral white adipose tissues of both chow-fed lean and a high fat diet-induced obesity in mouse." (PMID 39838122, 2025). "Toward that goal, we are currently conducting preclinical studies using GRK5-IN-2 to see if we can replicate our cell results in a mouse model of diet-induced obesity and to determine whether GRK5 inhibition could be a valuable translation target." (PMID 39838122, 2025). "Our cell data demonstrated that GRK5-IN-2 treatment resulted in decreased adipogenesis much like our GRK5 KO cell line, as well as decreased de novo lipogenesis, suggesting that GRK5 inhibition may be a therapeutic target for treating and preventing obesity." (PMID 38798474, 2024). "Thus, in this study, we aimed to determine whether GRK5 inhibition via GRK5-IN-2 in vivo could promote adipose tissue remodeling and improve metabolic health in diet-induced obesity." (PMID 40666930, 2025). "Our cell data demonstrated that GRK5-IN-2 treatment resulted in decreased and/or delayed adipogenesis much like our GRK5 KO cell line, as well as decreased de novo lipogenesis, suggesting that GRK5 inhibition may be a therapeutic target for treating and preventing obesity." (PMID 39838122, 2025). "However, the mechanisms by which GRK5 contribute to adiposity and obesity remain unclear." (PMID 38798474, 2024).
Obesity (continued). "In summary, GRK5-IN-2, a small molecule GRK5 inhibitor, did not mitigate diet-induced obesity or improve adipose tissue health but significantly reduced hepatic lipid accumulation." (PMID 40666930, 2025). "Thus, the lack of effect of GRK5-IN-2 on adipose inflammatory genes distinguishes it from Amlexanox, which exerts anti-inflammatory effects and attenuates diet-induced obesity." (PMID 40666930, 2025).
Hypertension (9 papers, 2015 to 2025). The presence of chronic increased pressure in the systemic arterial system. "High blood pressure, with its associated stressful effects on vascular wall integrity, can result in the potentiation of GRK5 expression within VSMCs." (PMID 30618771, 2018). "GRK5 is involved in cardiovascular diseases, including cardiac fibrosis, heart failure, and hypertension." (PMID 38961282, 2024). "Age, hypertension, vasopressor use, calculated POAF risk score, GRK5 rs2230345 T-allele, and GRK5 rs3740563 A-allele were associated with POAF despite beta-blocker prophylaxis." (PMID 36107363, 2024). "New association signals from cross-ancestry GWASs included, for example, variants at PROCR, GRK5 and F11 (thrombosis), LPA and ATP2B1 (lipid metabolism, hypertension and atherosclerosis), SWAP70 (membrane ruffling) and LAMC1 (cerebrovascular matrisome)." (PMID 36180795, 2022). "Both male and female hypertension in these GRK5-overexpressing mice was ablated upon treatment with the inhibitor of Gαi signaling, pertussis toxin." (PMID 30618771, 2018). "It has been demonstrated that elevation of GRK5 expression in vascular smooth muscle cells (VSMCs) can also induce the development of high blood pressure via altered β1-adrenergic receptor (β1-AR) and angiotensin II (Ang II) receptor signaling dynamics." (PMID 30618771, 2018). "Therefore, GRK5 may be a positive regulator of insulin resistance, which contributes to the pathogenesis of hypertension." (PMID 38961282, 2024). "GRK5, as with GRK2, for example, is also increased in lymphocytes from hypertensive humans and animal models of hypertension." (PMID 27390269, 2016).
breast carcinoma (8 papers, 2013 to 2025). "GRK5 was reported to serve as a tumor enhancer of breast cancer, of which the downregulation hampers the tumor progression." (PMID 35412954, 2022). "According to the Human Protein Atlas, 50% of the analysed breast cancer patients possessed elevated GRK2 or GRK5 expression, whereas the latter was shown to result in even worse prognosis concerning the 5-years survival rate." (PMID 31664083, 2019). "In this study, a breast cancer cell line screen revealed that GRK5 is mainly expressed in TNBC cell lines, which possess a mesenchymal like phenotype and are able to migrate." (PMID 31664083, 2019). "Consequently, we broadened our scope to include pan-cancer analyses, identifying studies that have explored the role of GRK5 in prostate cancer, breast cancer, and kidney cancer." (PMID 40722845, 2025). "GRK5 affects the migration of non-small cell lung cancer cells through vinculin, moreover, it shows a high expression in breast cancer cells, promotes breast cancer cell metastasis, and is therefore a target for breast cancer treatment." (PMID 36059531, 2022). "Additionally, a KD by a pool of GRK5 siRNAs was performed in another breast cancer (HS-578T) and two prostate cancer cell lines (DU-145, PC-3) and its effect on cancer cell migration was confirmed." (PMID 31664083, 2019). "Thus, we additionally investigated the effect of sunitinib on GRK5 and breast cancer cells in vitro." (PMID 31664083, 2019). "Therefore, the aim of this study was to elucidate the function of GRK5 in breast cancer and investigate whether the targeting of GRK5 could have a beneficial effect on cancer treatment." (PMID 31664083, 2019). "For example, downregulation of GRK2, GRK3, GRK5, and GRK6 promoted tumorigenesis and metastasis in Kaposi sarcoma, basal-like breast cancer, colon cancer, and medulloblastoma." (PMID 35769816, 2022). "GRK5 plays oncogenic roles in GBM, prostate, pancreas, renal cell, non-small-cell lung, and breast cancers." (PMID 35223984, 2021). "We observed that GRK5 is significantly higher expressed in mesenchymal-like breast cancer cells and that MDA-MB-231 cells, a metastatic, triple-negative breast cancer cell line, showed the highest GRK5 expression level of all analysed cell lines." (PMID 31664083, 2019). "However, the function of GRK5 in breast cancer and the involved GPCRs remain unclear." (PMID 31664083, 2019). "Our expression analysis in different breast cancer cell lines revealed that GRPR is significantly higher expressed in mesenchymal like breast cancer cell lines and correlates with the GRK5 expression." (PMID 31664083, 2019). "Analysis of public human breast cancer microarray data shows that only GRK3 and GRK5 isotypes are expressed at statistically significant lower levels in tumor cells compared to normal breast tissue." (PMID 27049755, 2016). "Nevertheless, the role of GRK5 in breast cancer has not been studied and the mechanism of action remains rather unclear." (PMID 31664083, 2019).
type 2 diabetes (8 papers, 2014 to 2025). "A genome-wide association study found a significant relationship of the single nucleotide polymorphism (SNP) rs10886471 in intron 3 of GRK5 with type 2 diabetes, but this was confined to Chinese Hans." (PMID 29773828, 2018). "We genotyped 3 common SNPs in intron 1 (rs1980030, rs10466210, rs9325562) and one SNP in intron 3 (rs10886471) of GRK5 in 2332 subjects at risk for type 2 diabetes." (PMID 29773828, 2018). "A genome-wide association study had showed G-protein–coupled receptor kinase 5 (GRK5) rs10886471 was related to the risk of type 2 diabetes mellitus (T2DM) through upregulated GRK5 mRNA expression." (PMID 24594703, 2014). "The first was a genome-wide association study, which found a significant relationship of the SNP rs10886471 in GRK5 with type 2 diabetes." (PMID 29773828, 2018). "Three tagging SNPs covering the first 4 kb of intron 1, a region highly enriched for gene-regulatory elements, and the SNP rs10886471, which was reported to be related with type 2 diabetes in Chinese Hans11 in intron 3 of GRK5 were genotyped and included in the analyses." (PMID 29773828, 2018).
diabetes (7 papers, 2014 to 2025). "After phosphorylation by GRK5, GPCRs negatively regulate the effects of the glucose metabolic signal, and causes abnormal blood glucose and diabetes." (PMID 24594703, 2014). "Thus, GRK5 is involved in the development and progression of several pathological conditions such as cardiac hypertrophy and failure, diabetes and cancer." (PMID 27326393, 2016). "Indeed, it has been shown that, the overexpression of GRK5 enhances the internalization of Glucagon Receptor, a GPCR that mediates hyperglycaemic effects of glucagon in Diabetes." (PMID 27326393, 2016).
Alzheimer disease (6 papers, 2017 to 2025). A progressive, neurodegenerative disease characterized by loss of function and death of nerve cells in several areas of the brain leading to loss of cognitive function such as memory and language. "In addition, case-control studies revealed that GRK5-Gln41Leu is associated with a lower risk of late-onset Alzheimer's disease." (PMID 29069820, 2017). "Our findings suggest that the GRK5-Gln41Leu mutant may resist tau hyperphosphorylation by promoting GRK5 membrane stability and, in effect, may contribute to lower Alzheimer's disease risk." (PMID 29069820, 2017). "We confirmed that GRK5 translocates from the cellular membrane to the cytosol in the hippocampus of Alzheimer's disease mice and that GRK5 deficiency promotes tau hyperphosphorylation, a hallmark of Alzheimer's disease pathology." (PMID 29069820, 2017). "Our work explores the relationship between G protein-coupled receptor kinase-5 (GRK5) single nucleotide polymorphisms and Alzheimer's disease risk." (PMID 29069820, 2017).